VCAM1 (vascular cell adhesion molecule 1)
Diseases named in the same sentence as VCAM1 in open-access papers (continued):
Sharing a sentence is not in itself a finding about the gene and the disease.
chronic kidney disease (15 papers, 2010 to 2025). Impairment of the renal function secondary to chronic kidney damage persisting for three or more months. "The VCAM-1 expression is up-regulated in renal proximal tubules in several renal chronic diseases, and the renal proximal tubule is targeted in the renal infiltration of T cells and monocytes which are rarely found in normal kidneys." (PMID 33407253, 2021). "HAVCR1 expression in PT_VCAM1 suggests that PT_VCAM1 likely represents a subpopulation of proximal tubular cells that is undergoing injury in situ, and expands in aging and chronic kidney disease." (PMID 33850129, 2021). "GPA patients with chronic kidney disease also had increased levels of VCAM-1, thrombomodulin and IMT." (PMID 29850964, 2018). "Consequently, future research should focus on investigating the expression of VCAM1 in various chronic kidney diseases." (PMID 39319258, 2024). "Moreover, GPA patients with chronic kidney disease were characterized by higher thrombomodulin level (11.7 [9.4–17.6) vs. 5.4 [4.4–6.9] ng/ml, p < 0.001) and VCAM-1 level (1258.2 [893.2–1457.7] vs. 747.4 [546.9–917.5] ng/ml, p < 0.001)." (PMID 29850964, 2018). "The top 25 upregulated genes showed evidence of matrix protein replacement with increased collagen synthesis (Col1a1 and Col3a1) and cellular infiltration (Cxcl1, Lyzs, Ccl5, Lyz2, Lyz, C3 VCAM1 and Ear2), consistent with the histological presence of chronic kidney disease in the mice." (PMID 22970174, 2012). "Chronic kidney disease (CKD) is associated with low-grade inflammation that activates nuclear factor–κB (NF–κB), which upregulates the expression of numerous NF–κB responsive genes, including the genes encoding IL-6, ICAM-1, VCAM-1, and MCP-1." (PMID 36012158, 2022). "Our study showed that the expression level of VCAM-1 and ICAM-1 increased in rats with chronic renal failure, which was inhibited by SKI treatment." (PMID 35674582, 2022). "Preclinical MR imaging using MPIO targeted against VCAM-1 (MPIO-αVCAM-1) has been shown to demonstrate acute and chronic endothelial activation in various clinically relevant contexts in mice, including chronic renal failure." (PMID 31440854, 2019). "Moreover, the urine levels of VCAM-1 were found to correlate with NIH renal pathology CI and the chronic kidney disease (CKD) stages (r = 0.30 and r = 0.39–0.50; p < 0.05 for all), suggesting a role as a marker of organ damage." (PMID 36233628, 2022).
colon carcinoma (15 papers, 2014 to 2025). "The expression levels of FAK, p-FAK, ICAM1, and VCAM1 were also upregulated with the overexpression of Sphk1 but downregulated with the reduction of Sphk1 in colon cancer cells." (PMID 28991193, 2017). "In breast and colon cancers, VCAM-1 mediates prometastatic tumor stromal interactions, proliferation, apoptosis and invasion, all of which ultimately contribute to malignancy and tumor progression." (PMID 24787244, 2014). "According to previous studies, insulin promotes colon cancer progression by increasing the expression of acyl-coenzyme A: cholesterol acyltransferase-1, and vascular cell adhesion molecule-1 in intestinal tumor endothelial cells, resulting in an inflammatory response that promotes malignancy." (PMID 36138391, 2022). "The promising results of this study, combined with the established involvement of VCAM-1 in CRC progression, warrant investigations into the therapeutic effects of anti-VCAM-1 antibodies on specific colon cancer lines." (PMID 40095109, 2025). "For colon cancer, identified biomarkers are CD15, CD104, CD324, CD326, CD49f, and for renal cancer, CD24, CD26, CD106 (VCAM1), EGFR, SSEA-3 (B3GALT5), SSEA-4 (TMCC1), TIM1 (HAVCR1), and TRA-1-60R (PODXL)." (PMID 36221114, 2022). "Ultimately, based on our MCIA, we identified CD15, CD104 (Integrin-β4), CD324 (E-cadherin), CD326 (EpCAM), and CD49f as biomarkers for colon cancer and CD24, CD26 (DPP4), CD106 (VCAM1), TIM-1, SSEA-3 (B3GALT5), SSEA-4 (TMCC1), TRA-1-60-R (PODXL) and EGFR for renal cancer." (PMID 36221114, 2022). "Additionally, it has been shown that CAFs from colon cancer promote IL8/CXCR2-mediated monocyte adhesion and attraction through upregulation of VCAM-1 expression and IL-6 production, and subsequently promote polarization to an M2 phenotype by expression of CD163 and CD206." (PMID 38606999, 2024).
idiopathic pulmonary fibrosis (15 papers, 2013 to 2026). Idiopathic pulmonary fibrosis (IPF) is a nonneoplastic pulmonary disease that is characterized by the formation of scar tissue within the lungs in the absence of any known cause. "Elevated VCAM-1 has previously been associated with mortality in SSc and clinical progression in SSc and idiopathic pulmonary fibrosis." (PMID 38366632, 2024). "Though elevated levels of VCAM-1 have been associated with pulmonary fibrosis its hyper-expression was seen in the early time points (days 1 and 14 post-PBI)." (PMID 33343356, 2020). "A previous study has shown that VCAM-1 is a TGF-β1 responsive mediator that partakes in fibroblast proliferation in idiopathic pulmonary fibrosis." (PMID 37985993, 2023). "High VCAM‐1 protein levels in the peripheral blood of patients with idiopathic pulmonary fibrosis can predict mortality." (PMID 35334492, 2022). "VCAM1 is upregulated in idiopathic pulmonary fibrosis, which can induce TGF-β1, and its main mechanism is to inhibit the proliferation of fibroblasts by reducing G2/M and S phases of cell cycle." (PMID 35370663, 2022). "VCAM-1 is an inflammatory mediator that promotes the development of lung fibrosis." (PMID 38590700, 2024). "But the expression pattern and the assumed putative role of VCAM‐1 as a contributor to idiopathic pulmonary fibrosis pathogenesis remains unclear." (PMID 35334492, 2022). "Interestingly, this study provides evidence, for the first time, of an association of VCAM-1, MCP-1 and ADMA with pulmonary fibrosis in RA-ILD+." (PMID 36601584, 2022). "VCAM-1 overexpression was found in various acute and chronic lung diseases, including acute respiratory distress syndrome, ventilator-induced lung injury and pulmonary fibrosis." (PMID 28747201, 2017). "Accordingly, the aim of this study was to explore the functional role of VCAM-1, MCP-1 and ADMA, assessing both protein and mRNA, as potential biomarkers of pulmonary fibrosis in RA-ILD+." (PMID 36601584, 2022). "A group of eight proteins has recently been propose as disease progression serum markers in Idiopathic Pulmonary Fibrosis (IPF): KL-6, surfactant protein A, and MMP-7, CCL-18, S100A12, IL-8, ICAM-1 and VCAM-1." (PMID 24216293, 2013). "Accordingly, we aimed to explore the role of vascular cell adhesion molecule-1 (VCAM-1), monocyte chemoattractant protein-1 (MCP-1) and asymmetric dimethylarginine (ADMA), key molecules in the vasculopathy, as potential biomarkers of pulmonary fibrosis in RA-ILD+." (PMID 36601584, 2022). "By analyzing the target interaction network VCAM1,RELA,CDK2,JUN,CDK1,HSP90AA1,NOS2, SOD1,CASP3,AHSA1, PTGER3 are at the core of the network, which can be regarded as the key targets of Astragalus polysaccharides in treating pulmonary fibrosis." (PMID 35370663, 2022).
osteoarthritis (15 papers, 2005 to 2024). A noninflammatory degenerative joint disease occurring chiefly in older persons, characterized by degeneration of the articular cartilage, hypertrophy of bone at the margins and changes in the synovial membrane. "NF-κB complex played a vital role in progression of osteoarthritis through RELA and VCAM1 which was linked with osteoarthritis as a precursor." (PMID 29731966, 2018). "Adhesion molecules ICAM-1 (CD54) and VCAM-1 (CD106) are expressed at higher levels in the synovial tissue of RA than in osteoarthritis and are implicated in the interaction between leukocytes and RA FLS that contributes to the synovitis." (PMID 16277688, 2005). "The inflammatory process is greatly influenced by the upregulation of vascular cell adhesion molecule type 1 (VCAM-1) in human osteoarthritis synovial fibroblasts (OASFs)." (PMID 32492888, 2020). "The development of osteoarthritis (OA) is characterized by synovial inflammation and the upregulation of vascular cell adhesion molecule type 1 (VCAM-1) in human osteoarthritis synovial fibroblasts (OASFs)." (PMID 32492888, 2020). "Other reports also indicate that interleukin-1β up-regulates the expressions of intercellular adhesion molecule-1 and vascular cell adhesion molecule-1 in osteoarthritis fibroblast-like synoviocytes via nuclear factor -κB-mediated mechanism." (PMID 26771387, 2016). "The aim of this study was to examine the distribution of stem cell markers (Notch-1, Stro-1 and VCAM-1) and of molecules that modulate progenitor differentiation (Notch-1 and Sox9) in normal adult human articular cartilage and in osteoarthritis (OA) cartilage." (PMID 19500336, 2009). "In addition, suppression of c-jun phosphorylation resulted in reduced AP-1 and VCAM-1 expression in osteoarthritis synovial fibroblasts." (PMID 39160581, 2024). "VCAM1 was expressed on cell surface of RA-FLSs, osteoarthritis (OA)-FLSs, or IL-4-stimulated dermal fibroblasts but not on non-stimulated dermal fibroblasts." (PMID 34281218, 2021). "E-selectin is highly expressed on endothelium in RA synovium, predominantly on venules and capillaries, whereas VCAM-1 and ICAM-1 are also expressed on other cell types, including ST macrophages, fibroblasts, and lymphocytes in RA synovium compared with osteoarthritis synovium." (PMID 22534470, 2012). "However, cells in mechanically damaged cartilage migrate to the injured site, and cells in early-stage osteoarthritis (OA) express surface markers such as CD105 and CD166 and exhibit stem-cell-related markers such as Notch-1, STRO-1, and vascular cell adhesion molecule-1 (VCAM-1)." (PMID 35296296, 2022).
acute kidney injury (14 papers, 2013 to 2025). Sudden and sustained deterioration of the kidney function characterized by decreased glomerular filtration rate, increased serum creatinine or oliguria. "The PT_VCAM1 cell state emerges after proximal tubule injury and is associated with acute kidney injury, aging, and DKD3,65." (PMID 36068241, 2022). "Nevertheless, Vcam1-positive PTCs, which serve as injury markers, were still detectable six months following acute kidney injury (AKI)." (PMID 40563434, 2025). "Studies in humans have characterized an adaptive proximal tubular (PT) cell phenotype, characterized by expression of VCAM1, that is present in the normal kidney but expanded in acute kidney injury (AKI) and CKD4,8–11." (PMID 40399382, 2025). "Vascular cell adhesion molecule-1 (Vcam1) is reportedly upregulated during kidney injury, promotes renal failure, and shows potential as a biomarker for kidney disease." (PMID 40516868, 2025). "To further characterize the role of PT_VCAM1 in acute kidney injury, we used a snRNA-seq mouse IRI48 dataset to predict the corresponding cell type for PT_VCAM1 in the injured mouse kidney." (PMID 33850129, 2021). "In keeping with this hypothesis, a recent mouse model of acute kidney injury found that, although the PT_VCAM1-positive cells may retain the ability to repair themselves, many of them experienced cell death." (PMID 39435665, 2024). "More interestingly, our study demonstrated that kaempferol could not only alleviate COX-2, but also inhibit the production of MCP-1, ICAM-1, and VCAM-1 at 24 h time point in CLP induced acute kidney injury." (PMID 37440431, 2023). "Our findings suggest that NF-κB plays a role in the maintenance of PT_VCAM1, which may be of clinical interest in designing therapies for acute kidney injury." (PMID 33850129, 2021). "Despite the fact that kidney samples originated from patients without kidney injury, the PT_VCAM1 population showed increased expression of kidney injury molecule-1 (KIM1, HAVCR1), which is a biomarker that is increased in acute kidney injury and chronic kidney disease." (PMID 33850129, 2021).
kidney damage (14 papers, 2012 to 2025). "Multiple logistic regression analysis reveals that baseline level of VCAM-1 is significantly associated with microvascular complications; diabetic neuropathy(p=0.028), retinopathy (p=0.007) and nephropathy(p=<0.001)." (PMID 36843591, 2023). "Circulating levels of cell adhesion molecules (VCAM-1) and selectins (P-selectin and L-selectin) are associated with the future development of microvascular complications, including diabetic neuropathy, retinopathy, and nephropathy." (PMID 41153721, 2025). "Circulatory levels of cell adhesion molecule (VCAM-1) and selectins (P-selectin and L-selectin) are associated with future development of microvascular complications including diabetic neuropathy, retinopathy and nephropathy." (PMID 36843591, 2023). "VCAM-1 was significantly associated with diabetic neuropathy, retinopathy and nephropathy." (PMID 36843591, 2023). "Increased levels of Ang-1, Ang-2, and VCAM-1 were correlated with the degree of kidney injury determined by kidney damage biomarkers." (PMID 40525140, 2025). "Selectins, integrins, intercellular cell adhesion molecules-1 (ICAM-1) and vascular cell adhesion molecule-1 (VCAM-1) are involved in leukocyte transmigration into kidney interstitium and promote kidney damage." (PMID 39506804, 2024). "Elevated VCAM-1 levels correlate with the severity of diabetic complications, including neuropathy, nephropathy, and retinopathy." (PMID 39727989, 2024). "Recent studies correlated the overexpression of pro-inflammatory (IL-1β, IL-6, TNF-α, and VEGF) and profibrotic genes (ICAM-1 and VCAM-1) with the appearance of nephropathies in diabetic patients." (PMID 36139749, 2022). "In this study, plasma concentration of ICAM-1 was elevated in microalbuminuric patients and in patients with overt nephropathy, plasma VCAM-1 was elevated only in patients with overt nephropathy." (PMID 26239462, 2015). "Additionally, PT VCAM1 represents a distinct subset of PT cells with abnormal expression of VCAM1 and HAVCR1, which is a specific cell subset associated with kidney damage in DN patients." (PMID 38978780, 2024). "However, in diabetic ICR mouse kidneys with Pg-LPS-induced nephropathy (LPS-STZ) the expression of VCAM-1 and the accumulation of FGF23 were observed in renal tubules and glomeruli, and the expression of E-selectin was observed in renal parenchyma and glomeruli." (PMID 33407253, 2021). "This OTA-induced oxidative stress promotes an inflammatory response by upregulating the expression of NF-κB, intercellular adhesion molecule-1 (ICAM-1) and vascular cell adhesion molecule-1 (VCAM-1), contributing to kidney damage." (PMID 40423338, 2025).
psoriasis (14 papers, 2010 to 2025). An autoimmune condition characterized by red, well-delineated plaques with silvery scales that are usually on the extensor surfaces and scalp. "Overall, the findings presented in this review highlight the important functions of VCAM-1 and E-selectin as significant indicators for assessing inflammation, disease severity, and cardiovascular risk in patients with psoriasis." (PMID 39859506, 2025). "In summary, this review highlights the importance of VCAM-1 and E-selectin as potential biomarkers for assessing inflammation, disease severity and cardiovascular risk in individuals with psoriasis." (PMID 39859506, 2025). "Consistently gene expression analysis in aorta samples showed elevated markers of endothelial activation, such as Icam1 and Vcam1 in psoriasis-like condition." (PMID 40599782, 2025). "In Teixeira’s study, it was observed that individuals with psoriasis had higher levels of VCAM-1 and E-selectin in their plasma, in comparison to the control group." (PMID 39859506, 2025). "VCAM-1 and E-selectin serum levels appear to be correlated with psoriasis severity as indicated by PASI and BSA." (PMID 32942670, 2020). "The results of our study demonstrate a possible impact of psoriasis itself and its systemic treatment on serum E-selectin and VCAM-1 levels." (PMID 32942670, 2020). "Understanding the impact of systemic psoriasis treatment on E-selectin and VCAM-1 serum levels will enable the selection of the appropriate therapy for both cardiovascular disease and skin lesions as coexisting conditions." (PMID 32942670, 2020). "This study aimed at determining VCAM-1 and E-selectin levels and evaluating their relationship with psoriasis severity compared to those in healthy controls." (PMID 32942670, 2020). "The objective was also to assess the impact of 12-week MTX and adalimumab (ADA) treatments on the VCAM-1 and E-selectin concentrations in psoriasis patients." (PMID 32942670, 2020). "Deregulation of intercellular adhesion molecule-1 (ICAM-1) and vascular adhesion molecule-1 (VCAM-1) was detected in the skin and synovial membrane of patients with psoriasis and psoriatic arthritis." (PMID 24396598, 2013). "In conclusion, the complex relationship between VCAM-1 and E-selectin in inflammatory diseases, particularly in the context of psoriasis, highlights their crucial functions in controlling leukocyte recruitment, activating endothelial cells, and disease pathogenesis." (PMID 39859506, 2025). "Vascular cell adhesion molecule-1 (VCAM-1) and E-selectin are involved in different inflammatory diseases and may be potential cardiovascular risk biomarkers in psoriasis." (PMID 39859506, 2025). "Moreover, the effects of systemic treatments and ultraviolet B (UVB) phototherapy on VCAM-1 and E-selectin levels in psoriasis patients highlights the potential to impact the severity of psoriasis and activation of endothelial cells." (PMID 39859506, 2025). "Increased expression of VCAM-1 was also found in the skin and plasma of patients with psoriasis." (PMID 34071993, 2021). "These genes may encode for TNF super family, IL-1, IL-6, IL-8, iNOS, major histocompatibility complex class 1 (MHC class 1) antigens, E-selectin, and vascular cell adhesion molecule 1 (VCAM-1), which are mostly involved in psoriasis." (PMID 32848730, 2020). "Several studies showed higher levels of E-selectin and VCAM-1 in psoriasis." (PMID 32942670, 2020). "Adhesion molecules include intercellular adhesion molecule-1 (ICAM-1) and vascular cell adhesion molecule-1 (VCAM-1), which play an important role in the infiltration of T cells into psoriasis lesion sites." (PMID 32659890, 2020). "Baseline VCAM-1 and E-selectin levels were significantly and negatively correlated with PASI and BSA in psoriasis patients." (PMID 32942670, 2020). "Baseline VCAM-1 and E-selectin levels were significantly correlated with disease activity (PASI and BSA) in psoriasis patients." (PMID 32942670, 2020).
psoriasis (continued). "The results of our study highlight a relationship between the severity of psoriasis as described via PASI and BSA with BMI and the levels of VCAM-1 and E-selectin." (PMID 32942670, 2020). "These dietary approaches can decrease levels of interleukin-6 (IL-6), vascular cell adhesion molecule-1 (VCAM-1), intercellular adhesion molecule-1 (ICAM-1), and low-density lipoprotein (LDL) in patients with psoriasis, thereby suppressing skin inflammation and abnormal keratinization." (PMID 39507900, 2024).